TLR2 (toll like receptor 2)
Diseases named in the same sentence as TLR2 in open-access papers (continued):
Sharing a sentence is not in itself a finding about the gene and the disease.
influenza (continued). "Interestingly a recent study on influenza demonstrated TLR2/6 signaling to induce a protective role in mice." (PMID 25340818, 2014). "These experiments suggest that TLR2-dependent inflammation induced by influenza infection promotes shedding of S. pneumoniae through nasal secretions, and the contact between infected and uninfected infant mice is sufficient to mediate bacterial transmission from host to host." (PMID 25166617, 2014). "The aim of this study was to evaluate whether selected polymorphisms of TLR2, TLR3 and TLR4 influence the incidence and clinical picture of pandemic A/H1N1/2009 influenza." (PMID 23151015, 2012). "As expected, CXCL10 and IFNα levels were highest in influenza infection, whereas IL6, IL10, IL1β, and PROK2 (which is highly inducible in macrophages by LPS and other TLR2/4 agonists) reached higher levels in the bacterial infections." (PMID 39395995, 2024). "Changes in expression of different toll-like receptors (TLRs) (TLR2, TLR3, TLR4, TLR7, TLR8, and TLR9) have been reported before in human monocytes and dendritic cells from seasonal influenza infected patients." (PMID 30682165, 2019). "In previous studies, the gut microbiome was determined to be a key modulator for metabolic disorders in TLR knockout mice, including TLR2 and TLR511, 17, and TLR5-mediated sensing of gut microbiota impacted antibody response to influenza vaccination." (PMID 27180604, 2016). "Here, we found that HIV-1 and gp120 produced a TLR2/4-dependent IFN-like effect towards influenza replication, revealed by the IFITM3-dependent HIV-1- or gp120-induced inhibition of influenza replication." (PMID 24978204, 2014). "For most other licensed vaccines, there is only indirect evidence implicating TLR function: Hib-OMPC – TLR2, meningococcal – TLR2, pertussis – TLR4, influenza – TLR7, measles – TLR2/TLR4." (PMID 23565115, 2013). "TLRs, such as TLR3, TLR7, and TLR8, are membrane-bound PRRs that recognize viral RNA: TLR3 detects double-stranded RNA (dsRNA), a byproduct of influenza replication, TLR7/8 sense single-stranded RNA (ssRNA) from the viral genome, while TLR2 and TLR4 recognize influenza-induced DAMPs." (PMID 40692679, 2025). "In addition, some studies have shown that TLR2, IFIT5, RSAD2, CLDN1, and HCLS1 play an important role in regulating the replication of influenza and other viruses in host cells." (PMID 37896995, 2023). "It has been demonstrated in mice that in the absence of TLR2 signalling, transmission of S. pneumoniae occurred more efficiently during co-infection with influenza." (PMID 34644311, 2021). "For instance, stimulation of other pattern recognition receptors that respond to influenza, such as TLR3, TLR7, and RIG-I, could affect pneumococcal transmission, as shown for TLR2." (PMID 25166617, 2014). "Indeed, complete TLR-deficient mice (due to a lack of TLR2, TLR4 and Unc93) showed significant deficits in CD5+ B-1 cell responses following influenza infection." (PMID 31433296, 2019). "Indeed, although TLR2 was not involved in the exaggerated lung inflammation elicited by S. pneumoniae in mice pre-exposed to influenza, the pulmonary immunopathology and lethality provoked by cell wall components of pneumococci were found to be mediated, at least in part, by this receptor." (PMID 23483993, 2013). "We have shown that the TLR-2 agonist PEG-Pam2Cys provides mice with immediate protection against influenza virus and does not impact the induction of influenza-specific immunity following subsequent exposure to virus, which provides both homotypic and heterosubtypic protection." (PMID 26097481, 2015).
leprosy (34 papers, 2006 to 2025). Leprosy is a chronic infectious disease affecting primarily the skin and peripheral nervous system. "It has been shown that while TLR2 SNP was associated with increased risk for leprosy, TLR1 and TLR4 SNP were associated with differential production with chemokine and cytokines." (PMID 37187734, 2023). "Our findings reinforce the idea of the participation of TLR1 and TLR2 polymorphisms in the immune response to leprosy." (PMID 36313452, 2022). "The TLR2 SNPs rs1339 and rs7656411 have been previously reported to be associated with susceptibility to leprosy and bronchiolitis obliterans, respectively." (PMID 33777838, 2021). "Kang and Chae reported that the TT genotype of the rs3804099/TLR2 polymorphism was associated with susceptibility to leprosy." (PMID 35141236, 2021). "In a CGAS, functionally relevant coding single-nucleotide polymorphisms (SNPs) of TLR1/TLR2 were studied in 543 Bangladeshi leprosy patients and 842 healthy controls, and the polymorphism N248S was found to be associated with leprosy." (PMID 32373110, 2020). "For instance, single-nucleotide polymorphisms occurring in the TLR2/1/6 axis have been reported to influence the course of chlamydiosis, leprosy and hepatitis B and C virus infections." (PMID 32576819, 2020). "In this study, we observed an association between the T allele of the markerrs3804099 at the TLR2 gene and susceptibility to leprosy perse comparing cases and controls." (PMID 28327786, 2017). "The innate immune recognition of M. leprae seems to be mediated by the toll-like receptor 2 (TLR2) and mutations/polymorphisms in TLR2 can affect host susceptibility to leprosy." (PMID 26305243, 2015). "Three polymorphisms in TLR2 (597C > T, 1350T > C, and a microsatellite marker) were analyzed in 431 Ethiopian patients with leprosy and 187 control subjects." (PMID 26793196, 2015). "Also, in the presence of the same TLR1 T allele, when the allele present is the TLR2 T allele, the data suggest protection against the development of leprosy, showing the predominance of the TLR2 polymorphism in the presence of the defective TLR1 allele." (PMID 36313452, 2022). "Also, in the TLR2 T>C (rs4696483) polymorphism, the T/T and C/T genotype had lower frequency in the leprosy patients than in the control group (7.2% vs. 26.8% and 39.6% vs. 48.2), suggesting protection from leprosy, whenever the T allele is present." (PMID 36313452, 2022). "This study suggests that polymorphisms in TLR1 and TLR2 are factors that may contribute to development/resistance of leprosy." (PMID 36313452, 2022). "Additionally, in TLR2 T>C (rs4696483) polymorphism, the T/T and C/T genotypes were observed at a lower frequency in the leprosy patients than in the control group (7.2% vs. 26.8% and 39.6% vs. 48.2%, p < 0.0001), suggesting protection against leprosy disease when the T allele is present." (PMID 36313452, 2022). "The high TLR2 expression associated with IL-10 levels, in the leprosy reaction groups, may be hypothetically related to the formation of TLR2/2 homodimers and/or TLR2/6 heterodimers linked to evasion mechanisms in downgrading reactions and pathophysiology of ENL." (PMID 31781675, 2019). "High IL-10 producing allele of TLR2 microsatellite might predispose household contacts to leprosy." (PMID 26793196, 2015). "RR specimens also expressed S100A12, which encodes an antimicrobial protein induced by TLR2/1L and IFN-γ in human macrophages, as well as IL12B and IL12RB2, known to be involved in host defense against leprosy." (PMID 40569678, 2025). "Furthermore, nerve injury in leprosy may be caused by TLR2 on Schwann cells." (PMID 38818380, 2024). "The evaluated SNVs show that the rs5743618 variant in the TLR1 gene, in combination with the rs5743708 SNV in the TLR2 gene and the rs5743810 SNV in the TLR6 gene, are related with the susceptibility to leprosy in this population." (PMID 37888601, 2023).
leprosy (continued). "A case–control study was conducted in a leprosy endemic region of Colombia (Norte de Santander) to investigate the potential association between single nucleotide variants of the TLR1, TLR2 and TLR6 genes and the development of leprosy." (PMID 37888601, 2023). "Based on the participation of Toll receptors in modulating the immune response to infection by M. leprae, we suggested that genetic variations in the TLR1, TLR2, and TLR4 genes are somehow associated with leprosy." (PMID 36313452, 2022). "For the TLR2 T>C (rs1816702), the T/T genotype was less frequent in leprosy patients than in the control group (2.6% vs. 7.7%) in the co-dominant genetic inheritance model, as well as the T allele (15.0% vs. 24.7%)." (PMID 36313452, 2022). "TLR2 T>C rs1816702 and TLR2 T>C rs4696483, the T/T and C/T genotype, respectively, were more frequent in the control group than in leprosy patients, suggesting protection from leprosy when the T allele is present (rs4696483)." (PMID 36313452, 2022). "TLR1G>T (rs5743618), TLR2T>C (rs1816702), TLR2 T>C (rs4696483), and TLR4 A>G (rs1927911) genotype and allele frequency distributions between leprosy patients and control group." (PMID 36313452, 2022). "In leprosy lesions, TLR2 was shown to mediate SC apoptosis, contributing to nerve injury characteristic of T1R." (PMID 34746168, 2021). "SNPs in TLR2 and TLR6 were previously associated with leprosy or tuberculosis, but their specific roles are less understood." (PMID 35141236, 2021). "The TLR1 and TLR2 expression levels were compared in all groups showing that these receptors in reaction-free leprosy MB group there were balanced expression (TLR1: 1.01 ± 0.23, TLR2: 1.22 ± 0.18; p = 0.267)." (PMID 31781675, 2019). "On the contrary, in the reaction-free leprosy group, interferon-gamma (IFN-γ) levels were dependent on the association between TLR2 and TLR1 (0.8735)." (PMID 31781675, 2019). "Schwann cells can also express TLR2 and the activation of TLR2 on these cells contributes to nerve damage in leprosy." (PMID 28162092, 2017). "Cytokine and chemokine profiles in leprosy patients according to differentgenotypes of TLR2 SNPs - In the analysis of cytokines and chemokinesproduction across the different genotypes of TLR2 markers we foundsignificant differences as described." (PMID 28327786, 2017). "The influence of GT microsatellite on the expression of TLR2 was measured in 88 leprosy patients, 95 household contacts, and 96 healthy controls." (PMID 26793196, 2015). "In some cases, such as TLR2 in the context of TB and leprosy and TLR4 in the context of TB, this abrogated function correlates unsurprisingly with increased susceptibility of the host to infection." (PMID 22529866, 2012). "Moreover, the use of molecular methods applied to identify single nucleotide polymorphism (SNP) of Toll-like receptors (TLRs), particularly TLR1, TLR2 and TLR4, have been reported to be associated with distinct leprosy clinical manifestations (19–23." (PMID 37187734, 2023). "TLR2 polymorphisms have been investigated in leprosy disease in different populations and have contributed to the TLR investigations in the innate immune response to leprosy." (PMID 36313452, 2022). "Moreover, genetic variants in TLR1, TLR2, TLR4, and TLR6 genes have been associated with autoimmune, infectious and inflammatory diseases, such as leprosy, pulmonary tuberculosis, atopic dermatitis, and systemic lupus erythematosus." (PMID 35141236, 2021). "Finally, we showed an unbalance in the expressions of TLR1 and TLR2, in the leprosy reaction groups, in contrast to reaction-free leprosy MB, the group which presented a balance in these expressions." (PMID 31781675, 2019). "It was possible to identify the expression of TLR2 in Schwann cells present in lesions from tuberculoid patients, in addition to cells that had undergone apoptosis in vivo, providing a link between innate immune response and nerve injury in leprosy." (PMID 29643852, 2018).
leprosy (continued). "In addition, lesions from leprosy patients with localized tuberculoid form displayed more strongly expression of TLR2 and TLR1 as compared with the lepromatous form of the disease." (PMID 29643852, 2018). "Interestingly, studies on the role of oxidized phospholipids in immune responses to leprosy have found that PEIPC was able to inhibit human monocyte function in a TLR2-dependent manner." (PMID 28138552, 2017). "In addition, genetic polymorphisms in TLR1, TLR2, and TLR4 are associated with leprosy and/or leprosy reactions." (PMID 23350010, 2013). "Although no disease association studies have been performed between TLR2 R753Q and leprosy, it would be very interesting to see if the results observed in the context of TB would also extend to M. leprae." (PMID 22529866, 2012). "When analyzing and comparing the expression of TLR1 and TLR2 in the same group, our findings demonstrated differences in these expressions, mainly in the reactional groups, in contrast to the quantitative balance of these receptors in the reaction-free leprosy MB group." (PMID 31781675, 2019). "IL-32 induction was measured, since it is specific to NOD2 versus TLR2/1 activation and is required to induce CD1b+ DC differentiation and cross-presentation, and its expression at the site of disease correlates with the self-limited versus progressive form of leprosy." (PMID 27297389, 2016). "To date, few pathologies have been genetically associated to TLR2 variants; an increased risk to develop prostate cancer has been traced to TLR1 (and TLR6 and 10 which are located on the same chromosomal locus, and more recently, resistance to leprosy was linked to the frequent I602S TLR1 allele." (PMID 19924287, 2009). "PB-type leprosy more commonly exhibits TLR1 and TLR2, while MB-type leprosy more commonly exhibits TLR4." (PMID 41239264, 2025). "In the context of leprosy, TLR1 and TLR2 are expressed more significantly in tuberculoid leprosy skin lesions, indicating their role in the immune response." (PMID 38818380, 2024). "In leprosy, cell surface heterodimers of TLR1/TLR2 and TLR6 recognize molecular patterns of M. leprae, such as peptidoglycan (PGN) and lipoarabinomannan (LAM), mediating APC activation." (PMID 34746168, 2021). "Additionally, this study suggested that polymorphisms in the TLR2 gene increase the risk of a patient developing reversal reactions; however, this polymorphism was not considered a risk factor for the development of leprosy per se." (PMID 26793196, 2015). "Currently there are four licensed vaccines that contain multiple TLR agonists, BCG that contains TLR2 and TLR4 agonists, Cervarix and Fendrix that contain alum and MPL, and Cadi-05 (Immuvac) (Mycobacterium indicus pranii) against leprosy." (PMID 26344621, 2014). "Toll-like receptors (TLR) 1, TLR2, TLR4, dendritic cell-specific intercellular adhesion molecule-3-grabbing non-integrin (DC-SIGN), and CD163 mediate the interaction between macrophages and M. leprae in leprosy, which increases IL-6 and IL-10 secretion." (PMID 41239264, 2025). "The differential expression among TLRs in the leprosy reaction groups, T1R and ENL, hypothetically suggests that the TLR2/2 homodimer formation may mediate the production of IL-10." (PMID 31781675, 2019). "Although the ligand for LILRA2 has not been identified, its activation inhibits TLR2/1-induced IL-12 release but maintains IL-10 release, and while the mechanism of LILRA2 activation during leprosy remains uncertain, LILRA2 is notably more highly expressed in LL than in TT lesions." (PMID 28162092, 2017).
ischemia (31 papers, 2009 to 2025). A hypoperfusion of the BLOOD through an organ or tissue caused by a PATHOLOGIC CONSTRICTION or obstruction of its BLOOD VESSELS, or an absence of BLOOD CIRCULATION. "Apparently, TLR2-mediated myocardial inflammatory responses in the non-ischemia areas and associated adverse extracellular matrix remodeling contributed to the worse dysfunction of aging hearts." (PMID 35493479, 2022). "We found that cardiac arrest and resuscitation induced a different glucose metabolism post-ischemia associated with the function of key immune factor TLR2 compared to the basal grade of glucose metabolism." (PMID 34779968, 2022). "TLR2 is upregulated and activated in neurons in response to ischemia, and focal cerebral ischemic injury is alleviated in TLR2-deficient mice." (PMID 26475712, 2015). "Neuroinflammation mediated by TLR2 or TLR4 was proved to play an active role in aggravating brain damage caused by ischemia/reperfusion." (PMID 24460643, 2014). "TLR2 expression in the brain is increased in rodent models of transient and permanent focal cerebral ischemia, as well as in vitro ischemia." (PMID 37102648, 2023). "Beyond participating in atheroma development, many studies have demonstrated that TLR2 can activate neutrophils and that free radical production results in coronary endothelial dysfunction after ischemia/reperfusion." (PMID 33574831, 2020). "Aside from the involvement of TLR2 in atheroma development, evidence shows that TLR2 contributes to coronary endothelial dysfunction after ischemia/reperfusion by activating neutrophils and free radical production." (PMID 27795867, 2016). "While some studies showed decreased brain injury in TLR2 KO mice after a focal ischemia, another study showed decreased neurological function and increased infarct size in TLR2 KO mice, suggesting a neuroprotective effect of TLR2." (PMID 25879213, 2015). "Our data reveals that treatment with IVIg significantly prevented ischemia-induced increased neuronal expressions of TLR2, TLR4 and TLR8." (PMID 25886362, 2015). "Our data has shown that IVIg not only prevented ischemia-induced increased expression levels of TLR2, TLR4 and TLR8 and attenuated its signalling cascades but also ischemia-induced cleavage of apoptotic protease caspase-3." (PMID 25886362, 2015). "In a model of ischemia, the TLR2-GFP-luciferase mice showed TLR2 activation as early as 6 hours after the ischemic event." (PMID 25147799, 2014). "The elevated expression of TLR4, TLR2, MyD88 and NF-κB is thought to be consistent with ischemia-evoked neuron injury and death through an inflammatory mechanism." (PMID 23434667, 2013). "We have previously demonstrated that TLR2 and 4, both of which mediate inflammation in response to alarmins, may play complimentary roles in muscle regeneration and angiogenesis after ischemia." (PMID 24844636, 2014). "Although TLR2 has been implicated in the pathogenesis of ischemia- and reperfusion-injury, the role of TLR2 in post-resuscitation disease has not been investigated so far." (PMID 24066159, 2013). "By contrast, some ligands of TLR4 or TLR2 could be used as preconditioning inducer, which would enhance cerebral resistance to severe ischemia and reperfusion." (PMID 23864765, 2013). "We and others have shown that TLR2 and TLR4 is needed for chemokine production of murine TECs that are exposed to simulated ischemia in vitro and that renal-associated TLR is an important initiator of inflammatory responses in ischemic acute renal failure in vivo." (PMID 19479087, 2009). "TLR2, TLR4, NF‐κB, cyclooxygenase‐2 (COX‐2), and serum TNF‐α were found to be correlated with ischemia‐induced cerebral inflammation and brain injury in rats." (PMID 37102648, 2023). "It is worth noting that there seems to be a certain contradiction to the results of other groups, who also examined the role of TLR2 and TLR4 in different ischemia/reperfusion models." (PMID 32833183, 2021).